HMGB1 (high mobility group box 1)
Diseases named in the same sentence as HMGB1 in open-access papers (continued):
Sharing a sentence is not in itself a finding about the gene and the disease.
lung carcinoma (continued). "Nevertheless, there is a lack of knowledge regarding the expression of HMGB1 and its correlation with the clinicopathological features of lung cancer." (PMID 29850505, 2018). "Furthermore, there was a correlation between HMGB1 expression with TNM staging and the postoperative survival of lung cancer patients, which was similar to the results of previous studies." (PMID 29850505, 2018). "Furthermore, circulatory HMGB1 levels are elevated in patients with COPD, especially in those with more severe airflow limitation or in cases complicated by comorbid lung cancer." (PMID 24758342, 2014). "In their study, the serum HMGB1 levels were higher in COPD patients with more severe airflow limitation (mean %FEV1, 49%) when compared with the results in the present study, and they found that patients with lung cancer had even higher levels of serum HMGB1." (PMID 24758342, 2014). "The serum level of HMGB1 in patients with nonsmall cell lung cancer (NSCLC) was significantly higher compared to patients with chronic obstructive pulmonary disease, suggesting that HMGB1 may be a useful marker for evaluating NSCLC progression." (PMID 23690821, 2013). "HMGB1 may be elevated not only by the presence of ILD, but also by lung cancer." (PMID 33980944, 2021). "However, the role of colocalization between HMGB1 and DRP1 in lung cancer migration is still unknown and needs further investigation." (PMID 33807275, 2021). "In conclusion, they pointed that HMGB1, VEGF, and survivin did not have any clinical significance in the prognosis of the survival time in lung cancer." (PMID 25699121, 2015). "Another study reported that treatment of mouse LLC lung cancer cells with CDDP (2.5 μM) could induce CRT exposure and ATP release, although it could not induce HMGB1 release." (PMID 37153795, 2023).
gastric cancer (119 papers, 2007 to 2025). A primary or metastatic malignant neoplasm involving the stomach. "In gastric cancer, elevated HMGB1 expression is strongly associated with resistance to cisplatin, while pharmacological inhibition of HMGB1 signaling markedly enhances cisplatin efficacy." (PMID 40969278, 2025). "For instance, GM-CSF from gastric cancer, HMGB1 via extracellular vesicles, and IL-6 from HCC-associated CAFs enhance PD-L1 expression in neutrophils through JAK-STAT3 signaling." (PMID 38760815, 2024). "Elevation of high mobility group box 1 (HMGB1), a typical damage-related molecule, is often associated with gastric cancer." (PMID 34026612, 2021). "This study aimed to evaluate the effects of single nucleotide polymorphisms (SNPs) in HMGB1 gene on the survival of gastric cancer (GC) patients." (PMID 27116470, 2016). "Hmgb1/2 inhibits genotoxic stress in polyglutamine diseases by interacting with mutant ataxin-1 and huntingtin protein; suppressing Hmgb2 expression causes gastric cancer cells to be less sensitive to chemotherapy." (PMID 35574435, 2022). "HMGB1 is also a diagnostic biomarker for the early stages of gastric cancer." (PMID 34456716, 2021). "In terms of association of genetic variants of HMGB1 and prognosis, previous reports showed that carrying AG or AA genotype of rs1045411 in HMGB1 gene was significantly associated with good overall survival in gastric cancer patients." (PMID 32489453, 2020). "Increased HMGB1 expression was associated with poor prognosis in patients with gastric cancer." (PMID 30292233, 2018). "Indeed, we also found that increased HMGB1 expression in gastric cancer patients was associated with poor outcomes." (PMID 30292233, 2018). "Association of HMGB1 SNPs and clinical outcome of gastric cancer patients." (PMID 27116470, 2016). "HMGB1 serum baseline levels of 227 patients undergoing gastrointestinal endoscopy differed significantly between the five created subgroups of nonmalignant diseases, high risk (e.g., adenomas), early gastric cancer, advanced gastric cancer and metastasized gastric cancer." (PMID 26854151, 2015). "PTBP1 negatively regulates this process, and reducing the expression levels of RAGE and HMGB1 can inhibit the glycolysis, proliferation, and migration ability of gastric cancer cells." (PMID 40579921, 2025). "In gastric cancer, HMGB1 knockdown reduces NF-κB activity and suppresses proliferation and invasion, confirming that NF-κB operates downstream of HMGB1 signaling." (PMID 41465435, 2025). "In gastric cancer, vincristine treatment induces autophagy, which subsequently promotes the extracellular release of HMGB1." (PMID 41465435, 2025). "In gastric cancer, exosomal high-mobility group box 1 (HMGB1) triggers neutrophil autophagy via the HMGB1/TLR4/NF-κB pathway, releasing pro-tumor factors like IL-1β and OSM that enhance EMT and migration." (PMID 41002568, 2025). "In particular, it was discovered for the first time that vitexin inhibits the proliferation, migration, invasion, and EMT of gastric cancer cells by downregulating the expression of HMGB1 in these cells." (PMID 40725244, 2025). "Elevated serum HMGB1 levels were found to correlate with tumor progression and metastasis in non-small cell lung and gastric cancers." (PMID 40331953, 2025). "In the hypoxic environment of gastric cancer, HMGB1 mediates the formation of NETs through the TLR4/p38 MAPK signaling pathway." (PMID 39849606, 2025). "In gastric cancer, chemotherapy-induced HMGB1 release elevates Mcl-1 transcript levels, preserving mitochondrial integrity and preventing vincristine-induced apoptosis." (PMID 41465435, 2025). "In gastric cancer cells, HMGB1 promotes mitochondrial fission and autophagy through the RAGE-mediated signaling pathway, further driving chemotherapy resistance and tumor growth." (PMID 39849606, 2025). "HMGB1 has furthermore been reported to be involved in migration and invasion of gastric cancer cells." (PMID 41161382, 2025).
gastric cancer (continued). "Conversely, gastric cancer cell-derived exosomes (GC-Exs) induce N2 polarisation through the HMGB1/TLR4/nuclear factor kappa-light-chain-enhancer of activated B cells (NF-κB) pathway, promoting metastasis." (PMID 41451221, 2025). "Gastric cancer-derived HMGB1-enriched exosomes activate the TLR4/NF-κB pathway in neutrophils, triggering the autophagy-dependent secretion of IL-1β and OSM." (PMID 40564191, 2025). "In summary, gastric cancer-exosomes promote autophagy and N2 neutrophil polarization via the HMGB1/TLR4/NF-кβ signaling." (PMID 40443670, 2025). "Exosomes derived from gastric cancer cells prolong the survival of TANs, induce the expression of inflammatory factors, trigger autophagy, activate TANs through the HMGB1/TLR4/NF-κB signaling pathway, and enhance gastric cancer cell migration." (PMID 39050856, 2024). "The analysis from GEPIA database (gepia.cancer-pku.cn/) showed that HMGB1 is obviously elevated in gastric cancer tissues." (PMID 38469295, 2024). "Consistent with previous reports, the expression levels of HMGB1 in gastric cancer tissues and cells were higher than those in adjacent lung tumor tissues and normal gastric epithelial cells." (PMID 38529373, 2024). "In gastric cancer, exosomes originating from gastric cancer cells expressed HMGB1, which prompted M2 macrophage polarization through the inhibition of the NF-κB signaling pathway." (PMID 38529373, 2024). "In gastric cancer cells, HMGB1 acts on RAGE to enhance Akt/mTOR and ERK signaling pathway phosphorylation, promoting cell migration." (PMID 38529373, 2024). "The HMGB1/RAGE axis regulates gastric cancer cell proliferation through the Akt/mTOR and ERK signaling pathways." (PMID 38529373, 2024). "In gastric cancer, cancer cell-derived extracellular vesicles (GC-EVs) transport high-mobility group box-1 (HMGB1), inducing PD-L1 expression on neutrophils and inhibiting T cell immunity." (PMID 38474175, 2024). "Clinical evidence suggests that high expression of HMGB1 and RAGE is associated with a significant decrease in the five-year survival rate in gastric cancer patients with diabetes compared to those with low expression." (PMID 38529373, 2024). "Increased HMGB1 release following autophagy induction in gastric cancer cells activates ERK, MAPK, AKT, and JNK signal pathways, thereby promoting cell proliferation." (PMID 37897664, 2024). "A significant elevation of serum HMGB1 was found up to 24.7 ± 13.6 ng/mL in gastric cancer patients." (PMID 39768997, 2024). "The tumor-promoting effects of HMGB1(+)-sEVs have been confirmed in malignancies, such as gastric cancer and esophageal squamous cell carcinoma." (PMID 37998605, 2023). "High mobility group box1 (HMGB1), an alarmin molecule is a regulator of autophagy and its expression is augmented during infection and gastric cancer." (PMID 37038107, 2023). "Here, glycyrrhizin, an inhibitor of HMGB1 decreased the intracellular H. pylori burden in gastric cancer cells." (PMID 37038107, 2023). "HMGB1 has a key function in autophagy stimulation in vital carcinogenesis, and it is mostly found in the cytoplasm of human gastric cancer cells with cell death and survival supervisory body." (PMID 36613714, 2022). "In ovarian and gastric cancer, HMGB1 knockdown can inhibit cancer cell proliferation, migration and invasion." (PMID 35379200, 2022). "Next, since the biological function of HMGB1 is related to its localization, we needed to identify the localization status of HMGB1 in gastric cancer cells when SEMA3B-AS1 was overexpressed or knocked down." (PMID 35273678, 2022). "The expression of MCL-1 in stomach is regulated by hypoxia-inducible factor 1 alpha (HNF1-α) in Helicobacter pylori-infected human gastric epithelium and HMGB1 in gastric cancer cells." (PMID 35221802, 2022). "Gastric cancer-derived exosomes can upregulate PD-L1 expression in neutrophils by transporting HMGB1, thereby inhibiting T cell function." (PMID 36341377, 2022).
gastric cancer (continued). "Gastric cancer cell-derived exosomes induce neutrophil autophagy and induce neutrophil N2 polarization via HMGB1/TLR4/NF-κB signaling to promote gastric cancer cell migration." (PMID 36365103, 2022). "HMGB1 contained in EVs released by gastric cancer cells induces autophagy and pro-tumor activation of neutrophils via the HMGB1/TLR4/NF-κB axis." (PMID 35269471, 2022). "In our study, glycated HMGB1 levels correlated with 4-HNE levels in both gastric cancer specimens and in vitro glycated cell lines." (PMID 34068442, 2021). "HuR, which has been found to be increased in gastric cancer, promotes HMGB1 expression at the translational level." (PMID 34026612, 2021). "In U937 cells, GLC or GLX induced 4-HNE and total HMGB1, but CML-HMGB1 levels were lower than in gastric cancer cell lines." (PMID 34068442, 2021). "Exosomes containing HMGB1 have been reported in gastric cancer and esophageal cancer to facilitate tumor malignancy." (PMID 34867338, 2021). "It is found that HMGB1-mediated autophagy decreases vincristine-induced apoptosis in gastric cancer partly via upregulation of Mcl-1, a Bcl-2 family member." (PMID 34933679, 2021). "Meanwhile, studies have also confirmed that miR-1179 can target HMGB1 to inhibit the proliferation of gastric cancer cells." (PMID 34903799, 2021). "For example, HMGB1 was found to be obviously upregulated in gastric cancer cells; HMGB1 silencing inhibited cell proliferation, colony formation, cell migration, and invasion and promoted cell apoptosis in vitro." (PMID 33817244, 2020). "HMGB1 was highly expressed in many cancer tissues and/or cells including prostate cancer, bladder cancer, human non-small cell lung cancer, gastric cancer, colon cancer, and also in PTC." (PMID 33817244, 2020). "Gastric cancer cell-derived EXOs carry HMGB1 and promote the migration of gastric cancer cells by inducing neutrophil autophagy through TLR4/NF-κB." (PMID 32551121, 2020). "B. The expression of exosomal HMGB1 in the serum samples of healthy controls and gastric cancer patients (n=3) was detected by using western blot." (PMID 30292233, 2018). "Recombinant HMGB1-treated neutrophils promoted the migration of gastric cancer cells and increased the expression of ATG7 and BECN1 genes in neutrophils." (PMID 30292233, 2018). "Gastric cancer cell-derived exosomes induced autophagy in neutrophils by activating NF-κB pathway through HMGB1/TLR4 interaction." (PMID 30292233, 2018). "Nonetheless, large cohort studies are warranted to determine the potential of exosomal HMGB1 as a biomarker for gastric cancer diagnosis and prognosis." (PMID 30292233, 2018). "The results of the mentioned study revealed the overexpression of HMGB1 protein in the cytoplasm of the gastric cancer cells, which is consistent with our findings in terms of increased expression." (PMID 30245980, 2018). "Silencing HMGB1 in gastric cancer cells confirmed HMGB1 as a key factor for GC-Ex-mediated neutrophil activation." (PMID 30292233, 2018). "To clarify the importance of HMGB1 in the pro-tumor activation of neutrophils, we silenced HMGB1 in gastric cancer cells by gene-specific siRNA and tested GC-Ex-induced neutrophil activation." (PMID 30292233, 2018). "C. Transwell migration assays for gastric cancer cells after treatment with supernatant from recombinant HMGB1-treated neutrophils." (PMID 30292233, 2018). "A. The expression of exosomal HMGB1 in the culture supernatants of tumor tissues and adjacent normal tissues (n=3) of gastric cancer patients was detected by using western blot." (PMID 30292233, 2018). "A recent study indicated benefits for combining both HMGB1 and IL-8 inhibition in experimental gastric cancer models." (PMID 29464075, 2018). "The results of western blot confirmed HMGB1 expression in GC-Ex from all of the tested gastric cancer cell lines." (PMID 30292233, 2018).
gastric cancer (continued). "It has been reported that the human serum HMGB1 levels are significantly and sequentially increased during gastric cancer progression." (PMID 27667993, 2016). "One study has indicated that autophagy antagonizes apoptotic cell death in gastric cancer cells through mediating high-mobility group box-1 (HMGB1) release into the extracellular milieu." (PMID 26910278, 2016). "Accordingly, blocking HMGB1 suppresses gastric cancer cell proliferation, whereas inducing IL-8 reverses this anti-tumor effect." (PMID 27667993, 2016). "HMGB1-induced autophagy promotes tumor resistance to chemotherapy, as shown in different models of malignancy, for example, osteosarcoma, leukemia, and gastric cancer." (PMID 26925422, 2016). "HMGB1 was actively released into the circulation of patients with gastric cancer and serum levels were significantly increased in gastric cancer patients compared to the level in the healthy volunteers." (PMID 25652880, 2015). "High HMGB1 expression has been reported in many cancers, such as prostate, kidney, ovarian, and gastric cancer." (PMID 26239046, 2015). "Immunohistochemistry and immunocytochemistry were used to determine the localization of HMGB1 in gastric cancer tissues, four gastric carcinoma cell lines (BGC-823, SGC-7901, MKN-28 and MKN-45) and a gastric epithelial cell line GES-1." (PMID 25652880, 2015). "In the present study, we showed that HMGB1 was highly expressed in human gastric carcinoma and primarily located in the cytoplasm of gastric cancer cells." (PMID 25652880, 2015). "HMGB1 expression in gastric cancer tissues and serum was significantly increased compared to the controls and healthy serum." (PMID 25652880, 2015). "RAGE knockdown also suppressed HMGB1-induced cell proliferation validating our presumption that HMGB1/RAGE interaction modulates gastric cancer cell proliferation." (PMID 25652880, 2015). "Gastric carcinoma cells showed an increased HMGB1 in the nuclei and cytoplasm, whereas GES-1 cells exhibited a lower HMGB1 with nuclear localization." (PMID 25652880, 2015). "In conclusion, the present study demonstrated that HMGB1 was highly expressed, particularly within the cytoplasm of human gastric carcinoma cells." (PMID 25652880, 2015). "HMGB1 appears to be a useful serological biomarker for early diagnosis as well as evaluating the tumorigenesis, stage, and prognosis of gastric cancer." (PMID 19476625, 2009). "The sensitivity and specificity of serum HMGB1 was 71% and 67% (cut-off value of 5 ng/ml) for the diagnosis of early gastric cancer, and 70% and 64% (cut-off value of 4 ng/ml) for the diagnosis of high-risk lesions, respectively." (PMID 19476625, 2009). "We investigated the correlation between the serum HMGB1 levels and the clinical and pathologic features of gastric cancer and evaluated the validity of HMGB1 as a potential biomarker for the early diagnosis of gastric cancer." (PMID 19476625, 2009). "Additionally, HMGB1 encapsulated by gastric cancer-derived EVs activates STAT3 signaling in neutrophils to upregulate PD-L1 expression, which suppresses T cell proliferation, activation and anti-tumor functions." (PMID 40908470, 2025). "HMGB1 promotes tumor angiogenesis in gastric cancer via an IL‐8‐mediated mechanism." (PMID 41354099, 2025). "Similarly, gastric cancer-derived EVs enriched with HMGB1 interact with TLR4 in neutrophils to activate NF-κB signaling, thereby activating the formation of immunosuppressive neutrophils." (PMID 40908470, 2025). "Additionally, gastric cancer cell-derived extracellular vesicles (GC-EVs) have been shown to transport high-mobility group box-1 (HMGB1), which activates STAT3 and upregulates PD-L1 expression in neutrophils." (PMID 40387965, 2025). "Also, Vitexin inhibited the gastric cancer in vivo and vitro by suppressing HMGB1-mediated activation of PI3K/Akt/HIF-1α signaling pathway." (PMID 41351800, 2025).